SCRIB (scribble planar cell polarity protein)
Description:
Scaffold protein involved in different aspects of polarized cell differentiation regulating epithelial and neuronal morphogenesis and T-cell polarization. Via its interaction with CRTAM, required for the late phase polarization of a subset of CD4+ T-cells, which in turn regulates TCR-mediated proliferation and IFNG and IL22 production (By similarity). Plays a role in cell directional movement, cell orientation, cell sheet organization and Golgi complex polarization at the cell migration front (By similarity). Promotes epithelial cell layer barrier function via maintaining cell-cell adhesion (By similarity). Most probably functions in the establishment of apico-basal cell polarity. May function in cell proliferation regulating progression from G1 to S phase and as a positive regulator of apoptosis for instance during acinar morphogenesis of the mammary epithelium. May regulate cell invasion via MAPK-mediated cell migration and adhesion. May play a role in exocytosis and in the targeting of synaptic vesicles to synapses. Functions as an activator of Rac GTPase activity. Represses translation of the downstream SCRIB protein. Translation of oSCRIB hinders SCRIB translation but does not completely abolish it, probably due to leaky scanning which allows the ribosome to bypass the weaker oSCRIB start codon and initiate translation at the stronger SCRIB start codon.
Synonyms: oSCRIB; CRIB1; KIAA0147; SCRB1; VARTUL; SCRIB1
Tractability: Small molecule: a structure with a bound ligand is known. Antibody: UniProt places it where antibodies can reach, with high confidence; its Gene Ontology location is reachable by antibodies, with high confidence; the Human Protein Atlas places it where antibodies can reach. PROTAC: UniProt records ubiquitination sites on it; ubiquitination databases record sites on it; its protein half-life has been measured.
Gene: Protein-coding gene on chromosome 8 (143,790,920 to 143,815,773, reverse strand). Ensembl gene ENSG00000180900.
Subcellular location: Cell membrane; Cell junction; Cell junction, adherens junction; Cell projection, lamellipodium; Cytoplasm; Postsynapse; Presynapse
Subcellular location (Human Protein Atlas): Cell Junctions; Plasma membrane; Nucleoplasm; Rods & Rings
Pathways (Reactome):
Signal Transduction: Asymmetric localization of PCP proteins; CDC42 GTPase cycle; RHOJ GTPase cycle; RHOQ GTPase cycle; RND2 GTPase cycle; RND3 GTPase cycle
Gene Ontology:
Molecular function: cadherin binding; protein binding; signaling adaptor activity; protein kinase binding
Biological process: activation of GTPase activity; apoptotic process involved in morphogenesis; cell migration; cell population proliferation; cell-cell adhesion; establishment of apical/basal cell polarity; negative regulation of mitotic cell cycle; neural tube closure; polarized epithelial cell differentiation; positive chemotaxis; positive regulation of apoptotic process; positive regulation of receptor recycling; protein localization to adherens junction; epithelial structure maintenance; establishment of T cell polarity; establishment or maintenance of epithelial cell apical/basal polarity; mammary gland duct morphogenesis; negative regulation of activated T cell proliferation; neurotransmitter receptor transport, endosome to postsynaptic membrane; positive regulation of type II interferon production; receptor clustering; establishment of cell polarity; synaptic vesicle clustering; synaptic vesicle endocytosis
Cellular component: adherens junction; anchoring junction; cell junction; cell leading edge; cell-cell junction; cytoplasm; extracellular exosome; nucleoplasm; plasma membrane; postsynapse; postsynaptic membrane; presynapse; presynaptic membrane; Scrib-APC-beta-catenin complex; basolateral plasma membrane; immunological synapse; postsynaptic density; cell-cell contact zone; lamellipodium; membrane; myelin sheath abaxonal region
Genetic constraint (gnomAD): Loss-of-function variants: 73 observed, 129.74 expected, observed/expected ratio (o/e) 0.56, 90% interval 0.47 to 0.68. The synonymous counts are far from expectation, so gnomAD's model fits this gene poorly and the ratio says little. Missense variants: 2,460 observed, 2,054.6 expected, observed/expected ratio (o/e) 1.2, 90% interval 1.16 to 1.24. Synonymous variants: 1,290 observed, 914.05 expected, observed/expected ratio (o/e) 1.41, 90% interval 1.35 to 1.48.
Homologues: Orthologues: chimpanzee SCRIB (99% identical), guinea pig SCRIB (88% identical), rat Scrib (87% identical), mouse Scrib (87% identical), dog SCRIB (85% identical), macaque SCRIB (78% identical), pig SCRIB (77% identical), tropical clawed frog scrib (63% identical), zebrafish scrib (61% identical), chimpanzee SCRIB (54% identical). Paralogues in human: LRRC7 (21% identical), ERBIN (21% identical), LRRC1 (20% identical), PHLPP1 (14% identical), PHLPP2 (13% identical), MFHAS1 (13% identical), LRRK1 (10% identical), LRRD1 (10% identical), SHOC2 (10% identical), LRRIQ4 (9% identical), PIDD1 (9% identical), LRRC40 (9% identical), and 19 more.
Diseases named in the same sentence as SCRIB in open-access papers:
SCRIB is named in the same sentence as 55 diseases in open-access papers, as found by Europe PMC text mining. Sharing a sentence is not in itself a finding about the gene and the disease. The quoted sentences say what the papers report.
breast cancer (23 papers, 2012 to 2025). A primary or metastatic malignant neoplasm involving the breast. "The cell polarity-related SCRIB protein complexes have been previously reported to play an important role in cancer progression in breast cancer, and their inhibition has been linked to a decrease in cell migration." (PMID 29032074, 2017). "In addition, higher expression of SCRIB mRNA was associated with poor prognosis of breast cancers and shorter survival of hepatocellular carcinoma patients." (PMID 33803371, 2021). "Also, the higher expression of SCRIB mRNA was significantly associated with poor prognosis of hepatocellular carcinoma and breast cancer patients." (PMID 32564009, 2020). "Thus, the inclusion/exclusion of specific SCRIB exons is a mechanistic hallmark of breast cancer, which could potentially be exploited to develop more efficient diagnostics and therapies." (PMID 27428426, 2016). "The expression of the cell polarity protein SCRIB can mediate endocrine resistance in ER+ breast cancer cells." (PMID 39833180, 2025). "Another study investigating breast cancer has proved that antisense circular RNA circSCRIB hindered the splicing of scribble (SCRIB) pre-mRNA, and interacted with SCRIB mRNA sequence, which resulted in the inhibition of SCRIB translation." (PMID 40093798, 2025). "In light of this complex molecular choreography, and its important role for breast cancer, it will be important to biochemically and structurally determine the binding characteristics of SCRIB, NOS1AP and KANK1 in future." (PMID 39613731, 2024). "SCRIB can be act as oncogene or tumor suppressing gene in different tumors, while the biological function of SCRIB in breast cancer was shown to promote mammary tumorigenesis." (PMID 37189064, 2023). "Since MYC expression is strongly induced by ER activation 17,18, our results suggest that SCRIB is regulated by the ER-MYC pathway in ER+ breast cancer cells." (PMID 35501367, 2022). "Comparative metabolite analysis identified eight metabolites, including leucine, that were downregulated in SLC3A2-KD and SCRIB-KD in ER+ breast cancer cells, suggesting that SCRIB and SLC3A2 targets leucine uptake in ER+ breast cancer cells." (PMID 35501367, 2022). "We found that the SCRIB gene is amplified in 14.42% of breast cancer patients in the TCGA dataset, and the gene amplification correlates with SCRIB mRNA expression in the TCGA breast cancer dataset." (PMID 35501367, 2022). "Here we report that SCRIB promotes cell proliferation in ER+ breast cancer cells in culture and in vivo." (PMID 35501367, 2022). "In fact, SCRIB is reported to be overexpressed at the mRNA and protein levels in multiple human cancers, including uterine and breast cancers, and the resultant mislocalization of SCRIB protein promotes tumorigenesis." (PMID 34535749, 2021). "This is consistent with studies on breast cancer cells and on mutant transgenic mice, showing that cytoplasmic SCRIB promotes cancer development by affecting subcellular localization of PTEN and activation of the Akt/mTOR/S6 kinase signaling pathway." (PMID 34503271, 2021). "Scribble (SCRIB), a cell polarity protein, was notably down‐regulated in tamoxifen‐ and paclitaxel‐resistant breast cancer cells relative to sensitive cells." (PMID 32281270, 2020). "We examined the use of MET on the proliferation and invasion of breast cancer cells that were resistant to TAM or TAX by focusing on changes in the Scribble (SCRIB)‐induced activation of the Hippo pathway." (PMID 32281270, 2020). "Taken together the results reported in this section show that SCRIB exon usage correlates with overall survival in breast cancer." (PMID 27428426, 2016). "In humans, deregulated expression and mislocalisation of Scribble complex members are associated with several epithelial cancers, including breast cancer, and human SCRIB is targeted by oncogenic viruses for degradation." (PMID 24852022, 2014).
breast cancer (continued). "SCRIB-associated tumor promotion is related to the PIK3CA (phosphatidylinositol-4,5-bisphosphate 3-kinase catalytic subunit alpha) pathway such as aPKC that is activated in 80% of 110 breast cancer patients particularly in invasive tumors." (PMID 40057606, 2025). "All sub-types of SCRIB-amplified breast cancers display mRNA over-expression of SCRIB." (PMID 36675340, 2023). "Thus, we examined the possibility that SCRIB mediates SLC3A2-SLC7A11 complex formation in ER+ breast cancer cells." (PMID 35501367, 2022). "In addition, overexpression of HA-tagged wild-type SCRIB in ER+ breast cancer cells promoted cell proliferation in suspension culture conditions." (PMID 35501367, 2022). "We and others have reported tumor-promoting roles of LLGL2 and SCRIB in breast cancer cells." (PMID 35501367, 2022). "However, controversially, the expression of SCRIB was decreased compared to normal tissue in oropharyngeal squamous cell carcinoma, breast cancer, uterine cervical cancer, lung cancer, and lymphoma." (PMID 35885485, 2022). "Taken together, our results identify a novel pathological role of SCRIB in ER+ breast cancer cells." (PMID 35501367, 2022). "Furthermore, elevated expression of SCRIB predicted shorter survival of breast cancer and gastric cancer patients." (PMID 33803371, 2021). "Our analysis of drug‐resistant breast cancer cells indicated that MET increased SCRIB expression, which then recruited MST1/2 and LATS1 to the plasma membrane, leading to YAP phosphorylation and its retention within the cytoplasm, and finally to inhibition of cell proliferation and invasion." (PMID 32281270, 2020). "Despite the absence of SCRIB mutations in clinical breast cancer, over-expression resulting from amplifications in its gene or other mechanisms may increase the cytoplasmic localization of the protein and activate the PI3K/AKT/mTOR pathway." (PMID 36675340, 2023). "Similarly, higher expression of SCRIB was associated with poor prognosis of estrogen receptor-negative and vimentin-positive breast cancer subtypes and clear cell renal cell carcinoma patients." (PMID 32564009, 2020). "Basal breast cancers frequently display over-expression of VANGL2 and SCRIB independently of the copy number status of their genes." (PMID 36675340, 2023). "SCRIB is located at locus 8q24.3, close to oncogene MYC, and is amplified in 10.3% of TCGA breast cancer cases." (PMID 36675340, 2023). "The mRNA expression of PCP-related genes VANGL2, NOS1AP, SCRIB, WNT11 and SMURF2 in VANGL2- or NOS1AP-amplified breast cancers (most cases are co-amplified) is heterogeneous in molecular sub-types." (PMID 36675340, 2023). "Both SCRIB and SLC3A2 are required for cell proliferation and tamoxifen resistance in ER+ cells identifying a new role for the SCRIB/SLC3A2 complex in ER+ breast cancer." (PMID 35501367, 2022). "In line with our results, a higher expression of SCRIB in human cancers has been reported in CRC, hepatocellular carcinoma, breast cancer, and prostate cancer." (PMID 35885485, 2022). "Considering that SCRIB-P305L mutant interacts with LLGL2, SCRIB works as a scaffold of SLC7A5-SLC3A2 complex to direct the membrane localization of SLC3A2 in ER+ breast cancer cells." (PMID 35501367, 2022). "In particular, we found that MET up‐regulated SCRIB, leading to YAP phosphorylation and localization to the cytoplasm, and ultimately to inhibition of the growth and invasion of TAM‐ and TAX‐resistant breast cancer cells." (PMID 32281270, 2020). "SCRIB upregulated by estrogen signaling interacts with SLC3A2 to modulate leucine amino acid transport, contributing to the proliferation and tamoxifen resistance of ER+ breast cancer cells." (PMID 39833180, 2025). "The cell polarity protein SCRIB regulates the intracellular localization of SLC3A2 in ER+ breast cancer cells, without affecting its expression level." (PMID 39833180, 2025).
breast cancer (continued). "The dependency evaluation of the cell lines with SCRIB, VANGL2 and NOS1AP amplifications with CRISPR and RNAi revealed several genes involved in breast cancer pathogenesis, such as FOXA1, ERBB2, PIK3CA and CDK4, to be among the top preferential essential genes." (PMID 36675340, 2023). "mRNA expression of VANGL2, NOS1AP and SCRIB is not prognostic of survival in breast cancer as a whole or in the subsets of luminal A, luminal B, HER2 and basal cancers (Log Rank p corrected for multiple comparisons >0.05; not shown)." (PMID 36675340, 2023). "In addition, VANGL proteins serve as the docking site for SCRIB and NOS1AP, and the VANGL/SCRIB/NOS1AP complex promotes cell migration in breast cancer cells." (PMID 36675340, 2023). "Unlike LLGL27, SCRIB protein was not differentially expressed and was detected in all types of breast tumors in ER+ and ER− breast cancer patients’ tissues and cell lysates." (PMID 35501367, 2022). "Unexpectedly, SCRIB and SLC3A2 form a quaternary complex with LLGL2-SLC7A5 to promote membrane assembly of the SLC7A5/SLC3A2 amino acid transporter complex, which is needed for leucine uptake and proliferation of ER+ breast cancer cells in culture and in vivo." (PMID 35501367, 2022). "Moreover, TET3 knocked-down cells under normoxia exhibited an identical alternative splicing pattern of ESRP1 targets (hMENA, SLK, SCRIB, RALGPS2, SLC37A2, FNIP1, CD44, and ARHGEF1) as the hypoxic breast cancer cells." (PMID 34362878, 2021). "Conversely, disabling SCRIB, e.g. by dislocation from the plasma membrane into the cytoplasm, impairs the SCRIB influence on the Hippo pathway and leads to increased TAZ stability, nuclear localization of TAZ, increased breast cancer cell proliferation and breast cancer growth." (PMID 39613731, 2024). "However, CRISPR and RNAi knockdown revealed no recurrent dependencies characterizing these cell lines with SCRIB, VANGL2 and NOS1AP amplifications that could suggest therapeutic avenues in breast cancers with these amplifications." (PMID 36675340, 2023). "We have previously demonstrated that SCRIB was frequently mislocalized in triple-negative breast cancers (TNBC) and that expression of a membrane localization defective SCRIB mutant (P305L) activates the Akt pathway to promote cell proliferation in breast cancer cells." (PMID 35501367, 2022).
cervical cancer (9 papers, 2004 to 2022). A primary or metastatic malignant neoplasm involving the cervix. "Interestingly, E6 has been further shown to cause degradation of the polarity protein SCRIB, and overexpression of SCRIB is associated with poor cervical cancer prognosis." (PMID 32670895, 2020).
spina bifida (6 papers, 2013 to 2025). A congenital neural tube defect in which vertebrae are not fully formed. "It found that deleterious mutations of SCRIB were associated with spina bifida, but unclear through what exact mechanism." (PMID 40666233, 2025). "The SCRIB gene that codes for the polarity protein SCRIBBLE has been identified as a risk gene for spina bifida, the most common type of neural tube defect, found at high frequencies in autistic patients, as well as other congenital anomalies." (PMID 35626639, 2022). "Mutations in SCRIB are described in patients with spina bifida, one of the most common forms of neural tube defect that is found at a high frequency in ASD patients." (PMID 35626639, 2022). "Actually, in our recently digenic PCP variants screen in 510 NTDs, PTK7, and SCRIB double heterozygous variants were identified in a spina bifida case." (PMID 30689296, 2019). "The number of confirmed functional SCRIB mutations identified in spina bifida in this study (3 of 192; 1.6%) is less than that identified in a previous craniorachischisis study (1 out of 36; 2.8%)." (PMID 23922697, 2013). "The number of patients with spina bifida carrying novel SCRIB mutations predict to be pathogenic in this study (5 of 192; 2.6%) is comparable to the previous study (1 out of 36; 2.8%)." (PMID 23922697, 2013). "We detected six SCRIB missense mutations among 192 spina bifida infants." (PMID 23922697, 2013). "A recent study reported that mutations in SCRIB were associated with craniorachischisis in humans, but whether SCRIB mutations contribute to increased spina bifida risk is still unknown." (PMID 23922697, 2013). "This study demonstrated that rare deleterious mutations of SCRIB may contribute to the multifactorial risk for human spina bifida." (PMID 23922697, 2013). "Furthermore, mutations in SCRIB SADH domains associated with spina bifida and cancer impact the stability of SCRIB at the plasma membrane, suggesting that SADH domain alterations may participate in human pathology." (PMID 25664942, 2015). "Our data indicate that SCRIB mutations may underlie the pathogenesis of human spina bifida." (PMID 23922697, 2013). "Yet another study investigated the role of variants in SCRIB, another PCP pathway‐associated gene, in modifying the risk for spina bifida and other NTDs." (PMID 40666233, 2025). "Discovery of heterozygous digenic deleterious variants in human NTD cases with spina bifida (i.e. PTK7/ SCRIB) and anencephaly (i.e. CELSR1/SCRIB; CELSR1/DVL3) strongly support the strategy of screening PCP genes to discover risk alleles contributing to human NTDs3,12." (PMID 33574475, 2021). "We sequenced the SCRIB gene in 192 infants with spina bifida and 190 healthy controls." (PMID 23922697, 2013). "We hypothesized that SCRIB mutations were associated with non-craniorachischisis NTDs, and investigated this hypothesis among infants born in California with spina bifida." (PMID 23922697, 2013). "We also screened for other PCP genes including CELSR1, SCRIB, and LRP6 in the 192 US spina bifida, but no double PCP damaging missense variants were found in our current analysis." (PMID 30689296, 2019). "SCRIB mutations may interact with mutations among other non-PCP genes, or other genetic and environmental factors, and contribute to the spina bifida phenotype observed here." (PMID 23922697, 2013).